IFNAR1 (interferon alpha and beta receptor subunit 1)
Diseases named in the same sentence as IFNAR1 in open-access papers (continued):
Sharing a sentence is not in itself a finding about the gene and the disease.
infection (continued). "Unexpectedly, mixed bone marrow chimeras had increased susceptibility to infection; three out of eight 50% CD11c-Ifnar1-/- chimeras died prior to day eight." (PMID 27327515, 2016). "Lung infection with C. burnetii in mice has a more severe course in WT compared to IFNAR1-deficient animals indicating that type I IFN signaling is disadvantageous in this infection model." (PMID 28082986, 2016). "The increase in lung viral load was accompanied by greater weight loss, a measure of infection severity: IFNAR1−/− mice started to lose weight at day 5, lost significantly more weight than infected wt mice, and had a slower recovery." (PMID 24648449, 2014). "Livers of Ifnar1-deficient mice contained a smaller fraction of inflammatory monocytes, important antibacterial effector cells, specifically following infection via the gastrointestinal route." (PMID 23840314, 2013). "The same phenotype was observed after infection with lower fungal doses of 0.5×105 Ca cfus, whereas increasing the fungal loads to 5×105 Ca cfus obliterated the protective effect of IFNAR1-deficiency." (PMID 22911155, 2012). "To study the significance of virus replication in phagocytic cells in vivo, we injected intraperitoneally (i.p.)and intravenously (i.v.)clodronate-loaded liposomes (CLL) to Ifnar1-deficient mice prior to infection with RVFV." (PMID 22163058, 2011). "Following inoculation with HAV, Ifnar1-/- mice (which have increased susceptibility to infection by this virus) become viremic, shedding virus in their feces; infected animals then develop acute hepatic inflammation (consistent with hepatocellular apoptosis) and exhibit elevated serum levels of ALT." (PMID 38478584, 2024). "This protection was most significant during the early stages of infection as indicated by the high levels of infectious virus recovered in the VW of IFNε-/- mice that closely mirrored levels observed in the highly susceptible IFNAR1-/- mice." (PMID 36897927, 2023). "IL‐15 treatment prior to infection could partially restore the deficiency of IFNAR1‐KO GMPs, indicating the importance of I‐IFN induction of IL‐15 production in myeloid cells." (PMID 37635627, 2023). "Furthermore, at day 5 post-infection, IFNAR1-deficient CD8+ P14 T cells continued to exhibit reduced Ezh2 expression, along with reduced expression of exhaustion-associated molecules, including PD1, TIM3, and TOX, compared to control cells." (PMID 36716323, 2023). "In contrast, using aged animals in an identical infection setting, we observed significantly increased weight loss in Ifnar1−/−, Ifnlr1−/−, and Ifnar1−/−Ifnlr1−/− mice compared with age-matched WT controls, sporadically even leading to lethal disease progression in case of Ifnar1−/−Ifnlr1−/− mice." (PMID 36129445, 2022). "Metabolic differences between Irf9-/- and Ifnar1-/- mice may underlie the different susceptibility of these mice against lethal infection with L. monocytogenes." (PMID 34237114, 2021). "Consequently, resistance to many viral pathogens requires IFNAR as determined by infection of mice deficient in IFNAR (Ifnar1-/-) and increased adverse reactions to attenuated viral vaccines observed in humans with inherited IFNAR deficiency." (PMID 34015056, 2021). "Our observation that i.d. infection of DKO Ifnar1-/-;Ifngr1-/- mice causes eschar formation highlights the critical importance of interferons in restricting R. parkeri in mice and may reveal a key molecular determinant of human disease." (PMID 34423779, 2021). "When mice were injected i.p. with anti-IFNAR1 antibody on the day of HSV-2 inoculation, disease progression was more rapid compared to isotype control-treated animals, and the mice succumbed to infection at a faster rate, in a manner similar to IFNAR1-deficient mice." (PMID 34047696, 2021). "We examined if i.v. and i.d. infections of WT and Ifnar1-/-;Ifngr1-/- mice could reveal a pathogenic role for R. parkeri Sca2." (PMID 34423779, 2021).
infection (continued). "Importantly, this age-dependent tissue-specific susceptibility to infection was found to be dependent on IFNAR1 expression." (PMID 32457247, 2020). "Moreover, i.a. inoculation of ZIKV in pregnant mice rendered more susceptible to infection using the anti-Ifnar1 antibody resulted in transplacental infection and delayed fetal development." (PMID 30333476, 2018). "Next we asked if longer-term infection is pathogenic, using Ifnar1 KO cultures." (PMID 28645311, 2017). "Both Tim1−/− Ifnar1−/− and Tim4−/− Ifnar1−/− double-knockout mice were susceptible to infection upon intravenous challenge with infected liver homogenate, with fecal HAV shedding and serum alanine aminotransferase (ALT) elevations similar to those in Ifnar1−/− mice." (PMID 28874468, 2017). "Since type I IFN signaling has been reported widely to impair bacterial clearance we examined gene expression from blood and tissues of wild type (WT) and type I IFNαβ receptor-deficient (Ifnar1-/-) mice at the basal level and upon infection with L. monocytogenes." (PMID 26918359, 2016). "IFNAR1-deficient mice infected intradermally with F. novicida respond by an increased IL-17 production compared to WT animals and, correspondingly, are more resistant against infection." (PMID 28082986, 2016). "Furthermore, we showed that Ifnar1-/- mice were more resistant to weight loss during S. Typhimurium secondary infection than WT mice, and allowed less translocation of S. Typhimurium across the intestinal wall." (PMID 27149619, 2016). "Similarly, IFNAR1 transcription was significantly decreased by Day 3 post-infection with GT-1b HCVser (P < 0.05), and was further associated with reduced protein expression in cells." (PMID 25826356, 2015). "However, autopsy was not consented in the current patient, but it is possible that IFNAR1 deficiency might increase the chance of invasive infection of heart endothelial cells." (PMID 35091979, 2022). "However, unlike the LCMV model, early blockade of type I IFN signaling led to more severe disease and a complete loss of viral control after HSV-2 infection, similar to infections performed on an IFNAR1-deficient genetic background, indicating an early antiviral role." (PMID 34047696, 2021). "Ifnar1 knockout, Ifnα/β−/−, A129) mouse model to allow for survival and recovery using the wild-type virus in order to examine whether a given mutation (detected in the epidemic genotype) increases infection morbidity and/or mortality." (PMID 33198111, 2020). "Notably, i.g. infection of Ifnar1−/− mice caused a slight but significant reduction of the fraction of inflammatory monocytes compared to Wt, whereas this cell type formed an equal percentage of CD45+ cells in both genotypes following infection through the peritoneum." (PMID 23840314, 2013). "Whether and how the higher neutrophil numbers and the more pronounced tissue destruction, which we have observed at the site of infection in the IFNAR1-/- animals, contribute to the increased susceptibility to S. pyogenes will be investigated in future studies." (PMID 21625574, 2011). "The proportion of symptomatic mice was also higher when anti-IFNAR1 mAb was administered 48 h before infection (66% versus 33%)." (PMID 41532622, 2026). "The results indicated that LSDV-encoded LSDV122 was associated with endogenous IFNAR1 and IFNAR2 following infection in MDBK cells." (PMID 41525414, 2026). "We did however observe higher bacterial burden in the spleen of Ifnar1-/- mice compared to WT at 3 days post-infection." (PMID 41499635, 2026). "Viral loads in animals that received anti-IFNAR1 mAb at any concentration or time point before infection were generally variable, but higher than in animals that received no mAb." (PMID 41532622, 2026). "At 14 days post-infection bacterial burdens in the spleen of WT and Ifnar1-/- mice was undetectable." (PMID 41499635, 2026). "Bacterial burden in the kidney of Ifnar1-/- mice was increased compared to WT at 14 days post-infection." (PMID 41499635, 2026).
infection (continued). "Based on the results of this pilot experiment, we decided to retain a 48-hour interval between the injection of anti-IFNAR1 mAb and infection, while also using higher viral doses for the further development of the model." (PMID 41532622, 2026). "In a final experiment, we assessed this condition (0.1 mg/mouse of anti-IFNAR1 monoclonal antibody administered 48 h before infection (ip) with 105 TCID50 of CHIKV) in mature adult mice, specifically 11-week-old female C57BL/6 mice." (PMID 41532622, 2026). "Groups of 7-week-old female C57BL/6 mice received anti-IFNAR1 mAb (ip) before infection (ip) with ONNV strain ONNV/UNK/SN/Dakar-234." (PMID 41532622, 2026). "A symptomatic disease (always mild, except for one mouse) was induced in 67% and 50% of mice receiving 0.1 mg of anti-IFNAR1 mAb 48 h or 24 h before infection, respectively." (PMID 41532622, 2026). "In vivo, the anti-IFNAR1 mAb MAR1-5A3 induces immunosuppression by blocking IFN-I receptors, rendering mice more susceptible to infection." (PMID 41532622, 2026). "For this, 7-week-old female C57BL/6 mice are first treated with anti-IFNAR1 mAb (ip, varying doses, 24 h or 48 h pre-infection) and then infected with CHIKV (ip, varying doses, CHIKV ECSA genotype)." (PMID 41532622, 2026). "The established infection model using two-day-old IFNAR1 knockout mice provides valuable insights into further investigations regarding its pathological injury mechanisms as well as the protective effects conferred by antibodies." (PMID 40733627, 2025). "For all the other IFNAR1 variants, the proportions of SARS-CoV-2-infected cells were similar to those for control cells at 24 and 48 h and various multiplicities of infection (MOI)." (PMID 39680367, 2025). "Ultimately, we established an E18 infection animal model utilizing 2-day-old IFNAR1-KO mice exhibiting immunocompromised functions." (PMID 40733627, 2025). "In summary, this study demonstrates that both male and female C57BL/6 IFNAR1−/− mice develop comparable clinical manifestations following WT YFV_HS306/2018 infection, with minor differences in recovery time." (PMID 41157597, 2025). "We therefore sought to directly compare the ability of the WT, sca2::Tn, and rickA::Tn strains to colonize internal organs by assessing the bacterial burden in the skin, spleen, liver, lung, and brain following i.d. infection of Ifnar1−/−; Ifngr1−/− DKO mice." (PMID 39819005, 2025). "Knock-out of IFNAR1 resulted in a roughly two-fold increase in infection over the NT control compared to the 4- to 5-fold increase observed in the CPSF6 knock-out cells." (PMID 41385587, 2025). "In contrast, all IFNAR1-KO mice succumbed within five days following intracranial injection, yielding a survival rate of 0% post-infection." (PMID 40733627, 2025). "Previous studies established Ifnar1-/- mice as a lethal model for USUV infection and noted clinical signs such as lethargy, progressive weight loss, ruffled fur, and hunching." (PMID 40694555, 2025). "In a mouse infection model, IFNAR1−/− mice infected with Francisella exhibited increased expression of IL-17A, enhanced neutrophil recruitment in the spleen, and improved bacterial clearance and survival rates." (PMID 40137714, 2025). "As expected, both Sp140−/− and Ifng−/− mice had up to 10-fold higher CFU than WT mice while Ifnar1−/−, Sp140−/−Ifnar1−/−, and Tbet−/− mice were as resistant as WT mice at 3 weeks post infection." (PMID 40463021, 2025). "Our identification of an E18 animal infection model utilizing IFNAR1-KO neonatal mice is consistent with findings from previous studies on E11 and E30 infections." (PMID 40733627, 2025). "Following an intraperitoneal in vivo infection with 2×108L. interrogans, we found a higher bacterial burden in the spleen of Ifnar1−/− mice compared to WT at 3 days post-infection." (PMID 40501870, 2025). "A reduction in IFNAR1 levels was apparent at 24 hours and levels decreased further at 36 hours post-infection." (PMID 40558091, 2025).
infection (continued). "The phosphorylation of STAT1 (pSTAT1), a canonical downstream effector of type I IFN signaling, was markedly reduced in Ifnar1–/– pBMDMs following MPXV infection, confirming the effective disruption of IFNAR1-dependent signaling in these cells." (PMID 41225161, 2025). "The dams were sacrificed on 3–9 days post-infection (dpi) to prevent a reduced health status normally occurring in Rag2-/-Il2rg-/- and Ifnar1-/- pregnant mice upon infection with high MCMV doses." (PMID 41288331, 2025). "Our in vivo infection of Sting1gt/gt and Ifnar1−/− mice with L. interrogans revealed a role for type I IFN in both the early control of bacterial replication as well as in chronic kidney colonization with L. interrogans." (PMID 40501870, 2025). "Ifnar1-/- mice also serve as a lethal infection model that can be used to study USUV neuropathogenesis or to compare the virulence of different USUV strains." (PMID 40694555, 2025). "Following the administration of 106 TCID50 E18 at 5 days post-infection (dpi), we evaluated the viral load in tissue homogenate supernatants from two mice per group, specifically C57 and IFNAR1-KO strains." (PMID 40733627, 2025). "Rescue of IFNGR1 levels was more apparent, but for IFNAR1, Tollip knockdown had a clear effect at 24 hours post-infection, and a more modest effect was evident at 36 hours post-infection." (PMID 40558091, 2025). "Blockage of type I IFN signaling starting 2 h before infection with anti-IFNAR1 mAb prevented the upregulation of MLKL and STAT1, another ISG, seen in wild type macrophages, without affecting the basal level of MLKL and STAT1." (PMID 40950000, 2025). "A novel infection model employing 2-day-old IFNAR1 knockout mice has been developed to examine the pathogenicity of Echovirus 30 (E30)." (PMID 40733627, 2025). "The levels of IL-1β in the two groups were comparable, whereas the level of IL-6 after infection was significantly lower in IFNAR1-/- mice than in WT mice." (PMID 40124358, 2025). "To do this, we used a multiplex bead-based immunoassay of mouse lung homogenates in WT, Ifnar1−/−, and Ifnlr1−/− mice day 1 post-infection." (PMID 38530032, 2024). "We have previously shown that IFNAR1 signalling is critical to the generation of functional CD8+ T cells in LCMV-Arm infection." (PMID 38543756, 2024). "Ifnlr1−/− mice exhibited higher lung HMPV titers than WT or Ifnar1−/− mice by day 5 and day 7 post-infection and delayed viral clearance, showing that IFN-λ contributes to limiting HMPV replication." (PMID 38530032, 2024). "Yet, intriguingly, the ∆44-UTR mutant maintained its fitness advantage in both Ifnar1-deficient cells and mice, suggesting WT CHIKV infection of murine cells is modulated by interactions of an IFN-I-independent antiviral host factor with the viral 3′ UTR." (PMID 38932154, 2024). "Wild-type C57BL/6 mice were pretreated with the anti-IFNAR1 antibody (MAR1-5A3) plus the anti-mLDLR antibody (R004) or control IgG intraperitoneally 24 h before infection." (PMID 38182887, 2024). "For instance, blocking IFNAR1 signalling with a monoclonal antibody in LCMV-CL13 infection results in a reduced frequency of virus-specific CD8+ T cells, which express PD-1 more highly." (PMID 38543756, 2024). "The stepwise decrease in NO production and the stepwise increase in CFU between B6 BMDMs to Ifnar1-/-and Il1r1-/- BMDMs to DKO BMDMs support the idea that NO production is associated with protection against rpoB-H445Y Mtb infection." (PMID 38603763, 2024). "Histologically, at 7 days post-infection, the Ifne-/- mouse testis showed signs of inflammatory damage comparable to that seen in the Ifnar1-/- mouse, which is unable to mount a type I interferon response entirely." (PMID 39621805, 2024). "A particularity of the disease is involvement of polymorphisms such as in IFNAR1 and CD207 that regulate antigen-presenting cell responses to infection." (PMID 37188663, 2023).
infection (continued). "For this purpose, the recently described model using immunocompetent mice in which IFNAR1 is transiently blocked to allow infection, appears to be promising." (PMID 38076464, 2023). "IFNAR1-disrupted cells, by contrast, were resistant to this decrease in dye dilution between days 3 and 6 post-infection, consistent with the expansion of this population during this time." (PMID 36909579, 2023). "Both control and IFNAR1-disrupted cells increased in number over the first 2 days of infection before reaching a plateau and then decreasing by day 4 post-infection, corresponding to the visual appearance of cytopathic effect in these cells." (PMID 36909579, 2023). "To better understand the basis for the fitness-decreasing effect of IFN-I signaling during SARS-CoV-2 infection, we next performed a detailed analysis of co-cultured control and IFNAR1-disrupted cells over the course of infection." (PMID 36909579, 2023). "Independent of 4’-FlU dose level, all treated animals of the RAG-1 KO and IFNAR1 KO groups survived, whereas all animals in the vehicle-treated groups developed severe clinical signs and succumbed to infection within 4 days." (PMID 37068076, 2023). "Our results also indicate that increased glucose uptake elicited by PbA-IE infection is critical to the induction of IFNAR1 signaling in BECs that in turn precipitate pathogenesis mechanisms operating in the initiation of clinical ECM in the mouse." (PMID 36993973, 2023). "We found that conditioned media from IFNAR1-disrupted cells contained greater numbers of infectious virions, with both a higher peak at day 2 post-infection and a longer persistence at subsequent time points." (PMID 36909579, 2023). "Following MHV68 infection of Ifnar1-/- mice, the expression of TNF-α, IFNγ, and IL-2 is decreased in antigen-specific CD8+ T cells, showing clear hallmarks of T cell exhaustion in the absence of type I IFN signaling." (PMID 37065193, 2023). "The increased expression of IFNAR1 with lower viral loads was also discovered in the knockdown cells after the infection of ZIKV." (PMID 37743411, 2023). "Removal of IFNAR1 from CD11c+ or CD4+/CD8+ T cells caused an increase in the titer of viruses, which persisted throughout the infection." (PMID 37766322, 2023). "While primary MHV-68 infection is fatal in conventional Ifnar1−/− mice (with different sensitivities depending on the mouse strain used), this novel inducible Ifnar1−/− mouse model allows the deletion of Ifnar1 upon establishment of MHV-68 latency." (PMID 36558888, 2022). "Further experimentation is needed to interrogate the potential mechanisms of the IFNAR1 response to different viral strain infections." (PMID 35056582, 2022). "R26CreERT2 x Ifnar1−/− mice were infected with MHV-68 H2bYFP, and after the establishment of latency (≥21 days after infection), 1 × 107 splenocytes were adoptively transferred into conventional Ifnar1−/− recipient mice." (PMID 36558888, 2022). "Prophylactic administration of 2 μg IFN-λ1/3 1 d prior to infection or a therapeutic regimen of 3 μg per day for 1 wk starting 1 d after infection efficiently prevented lethal disease progression in adult Ifnar1−/− mice." (PMID 36129445, 2022). "In anti-IFNAR1 IgG-treated mice, lower body weights and higher serum viral loads were observed during the whole course of infection compared with WT mice." (PMID 35612327, 2022). "We found that while Ifnar1−/− mice were able to slightly upregulate Ly6C expression on CD8+ Tn cells on d3 post-infection, the fraction of Ly6C+ cells in these mice was at least threefold lower than in Lm-infected wt mice." (PMID 34489451, 2021). "Irf1, Irf7, Irf8, and Irf9 transcripts were significantly induced by infection in Ifnar1-/- mice, whereas Irf6 transcripts (abundant in uninfected mice) were significantly down-regulated." (PMID 34591933, 2021). "To evaluate if intravaginal route of inoculation is capable of establishing infection, we inoculated pregnant IFNAR1-/- mice (n=5/group) at E12." (PMID 34410903, 2021).